MMP10 (matrix metallopeptidase 10)
Diseases named in the same sentence as MMP10 in open-access papers (continued):
Sharing a sentence is not in itself a finding about the gene and the disease.
lung carcinoma (continued). "In addition, Xiaoyuan Kong observed that NF-kb signaling activation and MMP-10 were reduced in the lung cancers of NPRA −/−mice, consistent with our results." (PMID 24885858, 2014). "Strikingly, these cultures also express elevated Mmp10 mRNA, but no increase in Mmp2, Mmp7, Mmp9, Mmp11, Mmp12 or Mmp14, other Mmp species commonly linked to lung cancer." (PMID 22545096, 2012). "Thus, Mmp10 is required for maintenance of a highly tumorigenic, cancer-initiating, metastatic stem-like cell population in lung cancer." (PMID 22545096, 2012). "Moreover, in lung cancer cells Rac mediates PKCι-induced secretion of MMP10, suggesting common downstream targets for PKC isozymes controlling invasion." (PMID 22384062, 2012). "Though Mmps have long been implicated in tumor progression and metastasis, we recently demonstrated that Mmp10 is overexpressed in human NSCLC and Kras-transformed BASC lung cancer-initiating cells, and that Mmp10 is required for transformed growth and invasion of human NSCLC cells in vitro." (PMID 22545096, 2012). "Cancer Stem Cell Signatures correlate with high Mmp10 expression in lung cancer." (PMID 22022614, 2011). "Given the importance of elevated Mmp10 expression in human lung cancer biology, we next assessed whether Mmp10 expression was also elevated in other forms of human cancer." (PMID 22022614, 2011). "A potential consequence of this limited molecular complementarity, in an in vivo setting characterized by multiple MMPs competing for a limited pool of TIMPs, may be an excess of residual active MMP-10, a situation that may contribute to pathogenesis in diseases such as lung cancer." (PMID 24073280, 2013). "Moreover, the MMP-1, MMP-2, MMP-9, and MMP-10 were found in the media of the ex vivo 3D lung model as well as in the serum of the blood samples collected from the superior vena cava and pulmonary veins of the lobectomy lung cancer specimens." (PMID 23028922, 2012). "For lung cancer, we select five essential genes, such as PYGB, C4BPA, SESN3, MMP10, IRS1." (PMID 33133130, 2020). "Given the unexpected role of Mmp10 in expansion of Kras-transformed mouse lung BASC and tumor initiating activity, we computationally explored the relationship between Mmp10 expression, cancer stem cell expression profiles and metastasis in human lung cancers." (PMID 22022614, 2011). "We found that Mmp10 is de-repressed by H3K9 KDMs; therefore, KDMi may prevent or delay the re-expression of these genes, potentially providing another angle to target Mmps in lung cancer." (PMID 30455465, 2018).
colon carcinoma (16 papers, 2012 to 2024). "Due to contradictory effects of MMP10 further investigations are needed to profoundly evaluate the role and differences of MMP10 in colon cancer and inflammatory bowel disease associated dysplasia." (PMID 27431388, 2016). "These tumor-promoting effects of MMP10 may explain, why high expression of MMP10 in sera of patients with colon cancer is associated with a dismal prognosis." (PMID 27431388, 2016). "Concerning promoter methylation status, all the differentially expressed MMPs showed statistical differences in promoter methylation between normal and colon cancer samples, except for MMP10." (PMID 34830271, 2021). "Expression of genes involved in angiogenesis and mitogenic responsiveness, comprising the EGFR ligand Epiregulin (Ereg), matrix metalloproteinase 10 (Mmp10), and cyclooxygenase 2 (Cox2) were up-regulated in colon tumors of Ripk3−/− mice." (PMID 27344176, 2016). "As we have observed for MMP7 and MMP10, we found that elevated abundance of serum MMP12 in colon cancer patients is associated with a significantly shortened overall survival." (PMID 27431388, 2016). "Multivariate analysis revealed high MMP10 serum levels to be an independent adverse prognostic marker in colon cancer patients." (PMID 27431388, 2016). "Strikingly, multivariate analysis revealed that an increased relative serum expression of MMP10 is an independent prognostic marker for impaired overall survival in colon cancer patients." (PMID 27431388, 2016). "Intriguingly, we were able to show that elevated levels of MMP10 in colon cancer patients ́ sera are related to an adverse overall survival by univariate and multivariate analysis." (PMID 27431388, 2016). "In a systematic analysis of MMP gene transcription, we identified the same three MMP genes [MMP1 (functional human homologue of mouse MMP13), MMP7 and MMP10] as target genes for acetylcholine-M3R activation in human colon cancer cell lines." (PMID 23617763, 2013). "MMP10 was a member of stromelysins, which was overexpressed and played a tumor-promotive role in oral cancer, ovarian cancer, pancreatic ductal adenocarcinoma, and colon cancer." (PMID 38374122, 2024). "Moreover, cagA-dependent H. pylori increased MMP-7 in HT29 colon cancer cells and MMP-10 in gastric epithelial cells." (PMID 36014933, 2022). "Serum levels of MMP10 are also an independent poor prognostic marker in patients with colon cancer." (PMID 35479956, 2022). "The MMP10 level can serve as a marker of poor prognosis in patients with colon cancer." (PMID 34301206, 2021). "Moreover we are the first to demonstrate that relative serum expression of MMP10 in colon cancer patients is an independent prognostic determinant for adverse prognosis." (PMID 27431388, 2016). "However divergent evidence exists that - opposing to MMP7 and MMP10 - MMP12 diminishes colon cancer growth in vitro and has a favorable impact on overall survival in colorectal cancer patients." (PMID 27431388, 2016). "To predict whether miRNAs target Mmp3, Mmp10, and/or Mmp13 in murine colon cancer cells, we first utilized the bioinformatics algorithms TargetScan, miRWalk, microRNA.org, and RNA22." (PMID 25742789, 2015). "Moreover, MMP10 is an independent prognostic marker in colon cancer patients." (PMID 27431388, 2016). "Expression patterns of MMP7, MMP10 and MMP12 in colon cancer patients ́ sera are different compared to serum specimens of healthy individuals." (PMID 27431388, 2016). "To our knowledge we are the first to demonstrate the influence of serum MMP10 and MMP12 on colon cancer patients ́ survival." (PMID 27431388, 2016). "Taken together our results propose that MMP7, MMP10 and MMP12 are increased in sera of colon cancer patients when compared to healthy donors and MMP12 seems to play a role in vascular invasion." (PMID 27431388, 2016).
colon carcinoma (continued). "The present investigation yielded MMP7, MMP10 and MMP12 serum levels in a homogenous group of colon cancer patients to be adverse prognostic molecular markers exerting valid multiplex bead-based immunoassay - technologies." (PMID 27431388, 2016). "Luminex based expression analysis revealed a significant overexpression of MMP7 and an overexpression of MMP10 and MMP12 in the sera of colon cancer patients compared to the healthy control group." (PMID 27431388, 2016). "The expression of MMP7, MMP10 and MMP12 were determined in serum samples of 78 colon cancer patients and 38 serum samples of healthy individuals using Luminex 100TM technology." (PMID 27431388, 2016). "In the present study we investigated the expression of MMP7, MMP10 and MMP12 in serum specimens in a homogenous collective of colon cancer patients with regard to clinicopathological characteristics and patients ́ prognosis." (PMID 27431388, 2016). "In summary, our results imply a significant influence of serum MMP7, MMP10 and MMP12 in human colon cancer dissemination with considerable impact on overall survival." (PMID 27431388, 2016). "After having confirmed differences in the expression of MMP7, MMP10 and MMP12 concentrations in colon cancer patients ́ serum samples and serum samples of a healthy control group we correlated these results with patients’ overall survival." (PMID 27431388, 2016). "Other markers of Paneth cells, such as secretory phospholipase A2 (PLA2G2A), MMP10 and MMP13, were also up-regulated, confirming that these cells are a cellular component of colon tumors, which is in agreement with previous reports." (PMID 26517809, 2015). "Previously, in human colon cancer cell lines, we showed that of the ~25 known MMP genes, acetylcholine treatment selectively induced robust transcription of MMP1, MMP7 and MMP10." (PMID 23617763, 2013). "The effect of IL-1β and IP6 on the expression of mRNA of MMP-1, MMP-2, MMP-3, MMP-9, MMP-10, and MMP-13 and that of their tissue inhibitors TIMP-1 and TIMP-2 in colon cancer cells using real-time QRT-PCR assay was determined." (PMID 22415590, 2012). "Moreover overexpression of MMP7, MMP10 and MMP12 in colon cancer patients ́ sera displayed a significantly impaired overall survival." (PMID 27431388, 2016). "Similarly, we observed a higher abundance of MMP10 (p = 0.128) and MMP12 (p = 0.544) in colon cancer patients` sera as compared to serum specimens of healthy individuals." (PMID 27431388, 2016). "As for MMP10 until now there are no studies assessing MMP12 expression in colon cancer patients ́ sera in regard with overall survival." (PMID 27431388, 2016). "Until now, there is no study which reports that overexpression of MMP10 in colon cancer patients ́ sera is correlated with survival." (PMID 27431388, 2016). "Furthermore, overexpression of MMP7, MMP10 and MMP12 in colon cancer patients ́ sera correlates with a dismal prognosis and may help to stratify patients into different risk groups." (PMID 27431388, 2016). "We thus further analyzed the data from TCGA and showed that HPSE is positively correlated with the expression of MMP1 in colon cancer (r = 0.3476, p < 0.0001) and rectal cancer (r = 0.3428, p < 0.0001), but not MMP7, MMP10, and MMP13." (PMID 31001480, 2019). "However, to our knowledge until now there is no study assessing serum MMP10 and MMP12 level in a homogenous collective of colon cancer patients’ sera in regard to overall survival." (PMID 27431388, 2016).
ovarian carcinoma (16 papers, 2014 to 2025). A malignant neoplasm originating from the surface ovarian epithelium. "Secondly, the risk of ovarian cancer increased with age in association with MMP3, MMP10, MMP7, TIMP3, POX/PRODH, PYCR1, PYCR3 to indicate degenerative histological changes." (PMID 38397798, 2024). "There is little research into the role of MMP10 in ovarian cancer, but it has been reported to be upregulated in this tumor as well, and it is known to be associated with cancer progression." (PMID 36012171, 2022). "In our study, we noted an increase in MMP10 expression in fibroblasts following treatment with exosomes derived from ovarian cancer cells." (PMID 36012171, 2022). "In our research, we noted an increase in MMP2 and MMP10 expression under the influence of exosomes derived from ovarian cancer cells." (PMID 36012171, 2022). "It has been reported that MMP10 plays a role in maintaining cancer stem-like cells /cancer-initiating cells and platinum resistance in epithelial ovarian cancer by activating Wnt signaling pathway." (PMID 35000533, 2022). "Co-transfection of TCF21 expression plasmid with miR-205 mimic diminished the inhibitory effect of TCF21 on MMP-2 and MMP-10 in ovarian cancer cells." (PMID 28476165, 2017). "Our results showed that MMP-2, MMP-7, MMP-9 and MMP-10 expression were significantly up-regulated in ovarian cancer tissue compared with normal ovarian tissues." (PMID 28476165, 2017). "MMP10 is generally expressed in ovarian cancer cells, but it is barely expressed in normal organs except for the uterus." (PMID 27072580, 2016). "To address the significance of the expression of MMP10 in clinical samples, we stained 122 epithelial ovarian cancer specimens immunohistochemically using an anti-MMP10 antibody." (PMID 27072580, 2016). "In Cis-resistant A2780 ovarian cancer cell line increased expression of MMP10 has also been observed." (PMID 24804215, 2014). "We are now the first research team to determine plasma levels of MMP-10 in ovarian cancer patients." (PMID 40565125, 2025). "In cervical and ovarian cancer, MMP10 is known to be involved in tumorigenesis and metastasis." (PMID 36650344, 2023). "Additionally, MMP10 was found to activate canonical Wnt signaling by inhibiting Wnt5a in chemotherapy-resistant ovarian cancer." (PMID 35000533, 2022). "TCF21 inhibited MMP-2 and MMP-10 and decreased ovarian cancer cell invasion." (PMID 28476165, 2017). "Therefore, the aim of this study was to evaluate the concentrations and diagnostic usefulness of selected enzymes from the matrilysin group (MMP-7, MMP-26) and stromelysins (MMP-3 and MMP-10) in the most common histological type of ovarian cancer—the serous type." (PMID 40565125, 2025). "Overexpression of MMP10 has been reported to promote invasion, metastasis and regulate stemness of cancer cells through activation of Wnt signaling pathway in head and neck, and ovarian cancer, and promote tumor progression by regulating angiogenic and apoptotic pathways in cervical cancer." (PMID 36650344, 2023). "Targeted inhibition of MMP-7 and MMP-10 may provide potential ovarian cancer therapeutic strategy." (PMID 28538838, 2017). "Statistically significant positive correlations in the ovarian cancer group were observed between MMP-26 and MMP-10 (r = 0.2168; p = 0.0101)." (PMID 40565125, 2025). "Ovarian cancer patients have elevated concentrations of MMP-7, MMP-26, MMP-10 as well as CA125 and HE4 in the total group and subgroups (stage I + II, and III + IV)." (PMID 40565125, 2025). "The presence of MMP-7, MMP-26, MMP-3, MMP-10, and MMP-11 expression has been previously confirmed in biopsy material from ovarian cancer patients." (PMID 41007705, 2025). "Most of the tested metalloproteinases upregulated mRNA expression in both FIGO I/II and FIGO III/IV stages of ovarian cancer (MMP1, MMP13, MMP2, MMP9, MMP10, MMP7, MMP12 and MMP14) indicating profound modifications of the extracellular matrix." (PMID 38397798, 2024).
ovarian carcinoma (continued). "In fibroblasts treated with exosomes from untreated ovarian cancer cells, a more significant increase in MMP2 and MMP10 expression was observed for the exosomes derived from the TOV-21G lineage." (PMID 36012171, 2022). "A previous study showed that MMP10 was expressed at higher levels in cisplatin-resistant sublines, CP70 and CP200, than in the parental ovarian cancer cell line A2780." (PMID 27072580, 2016).
colitis (15 papers, 2012 to 2025). Inflammation of the colon. "Loss of miR-148/152 can upregulate MMP10 expression, leading to intestinal barrier disruption and promoting the occurrence and development of colitis and colitis-associated colorectal cancer." (PMID 39883700, 2025). "Inhibition of MMP-10 activity via siRNA or blocking associated signaling resulted in the amelioration of colitis." (PMID 35392084, 2022). "Specifically, differential expressed genes (DEGs) related to colitis such as Mmp10, Tnfaip3, Lcn2, Serpine1, and Pla2g4f were upregulated in the colon tissue of colitis mice in DVF group." (PMID 38172943, 2024). "Bone marrow transplantation experiments showed that MMP10 derived from bone marrow is involved in colitis severity." (PMID 35432477, 2022). "Using the same mouse model, we further assessed the mRNA expression levels of Mmp3, Mmp10, and Mmp13 using quantitative real-time PCR (qPCR) of samples of mouse colitis tissue as well as CAC and normal colon tissues." (PMID 25742789, 2015). "This is important as MMP-10 was found to decrease inflammation in a mouse model of experimental colitis." (PMID 24101903, 2013). "MMP10 is produced predominantly by infiltrating myeloid cells in murine and human colitis." (PMID 35432477, 2022). "In animal models of experimental colitis, MMP10 seems to promote mucosal healing, and in its absence due to persistent colonic inflammation, dysplastic lesions could be promoted." (PMID 30417021, 2018). "Moreover, the levels of Mmp3, Mmp10, and Mmp13 proteins were also upregulated as determined with immunohistochemistry and western blotting of mouse colitis tissues and CAC tissues compared with normal colon tissues." (PMID 25742789, 2015). "Our findings corroborate that MMP10 and MMP3, regulated by IL-17 and involved in the inflammation-cancer relationship, become upregulated, enhancing IL-17 signal transduction and the release of inflammatory mediators, thus facilitating the development of colitis-associated colorectal cancer." (PMID 40595862, 2025). "Matrix metalloproteinase (MMP)-10, IL-17A, FGF-19, IL-10, and CXCL9 were increased in patients with exclusive colonic inflammation, that is, UC and colonic CD, compared to patients with exclusive ileal inflammation, that is, ileal CD." (PMID 39495605, 2025). "Comprehensive bioinformatics analysis using RRA, WGCNA, and Cytoscape, as well as in vivo validation using a classic mouse model of colitis revealed CXCL1, IL1B, MMP1, and MMP10 as signature genes of active UC." (PMID 35392084, 2022). "Most MMPs, such as MMP-2, MMP-3, MMP-7, MMP-9, MMP-10, MMP-12, and MMP-13 are increased in colitis and CAC." (PMID 36776395, 2022). "Our array data showed that metalloproteases and chemokines such as MMP10, MMP13, the CCs and CXCs are involved in the pathogenesis of DSS colitis." (PMID 22509329, 2012). "With a lack of MMP-10, susceptibility to DSS-induced colitis increases, and prolonged IBD may eventually lead to dysplasia." (PMID 36776395, 2022).